GSK3B (glycogen synthase kinase 3 beta)
Diseases named in the same sentence as GSK3B in open-access papers (continued):
Sharing a sentence is not in itself a finding about the gene and the disease.
cholangiocarcinoma (10 papers, 2013 to 2026). A carcinoma that arises from the intrahepatic biliary tree (intrahepatic cholangiocarcinoma) or from the junction, or adjacent to the junction, of the right and left hepatic ducts (hilar cholangiocarcinoma). "Our previous study demonstrated that the acetylcholine (Ach)/CHRNA5 axis promotes PNI progression in cholangiocarcinoma by upregulating BDNF expression through activation of the CAMKII/GSK3β/β‐catenin signaling pathway." (PMID 41556039, 2026). "Since the Wnt/β-catenin signaling pathway was previously reported as a vital regulatory factor in cholangiocarcinoma, the key pathway-related proteins, including Wnt3a, phosphorylated GSK3β, and β-catenin, were detected in HCCC-9810 cells after FOXP1 overexpression or knockdown." (PMID 38279090, 2024). "Interestingly, β-escin increases cholangiocarcinoma cells line sensitivity to chemotherapy, by inducing GSK-3β phosphorylation and dephosphorylation at tyrosine-216 and serine-9, respectively, leading to β-catenin degradation." (PMID 29379583, 2017). "The cross-talk role of Wnt/β-catenin and PI3K/Akt signaling pathway, with GSK-3β as the key enzyme bridging these pathways, may contribute to the inhibition of cholangiocarcinoma cells by hUC-MSCs." (PMID 23646150, 2013). "The effect of an inductor of GSK3β degradation was tested in combination with chemotherapy on cholangiocarcinoma (CCA) cells and was shown to enhance the effect of classical chemotherapy." (PMID 31921125, 2019). "GSK-3β plays an important role in CCA, by mediating the cross-talk of PI3K/AKT and WNT/β-catenin pathways directly controlling cell growth in a cholangiocarcinoma setup." (PMID 29379583, 2017).
clear cell renal cell carcinoma (10 papers, 2017 to 2026). "In summary, our results suggest that NAT10 mediates ac4C acetylation of NFE2L3 mRNA, promotes its mRNA stability, regulates the LASP1-AKT/GSK3β/β-catenin axis and promotes the progression of renal clear cell carcinoma." (PMID 40169553, 2025). "Additionally, VHL mutation-mediated SALL4 overexpression promoted clear cell renal cell carcinoma (ccRCC) cell proliferation, colony formation, cell cycle progression, migration, invasion, tumorigenicity, and tumor vascularization through modulating Akt/GSK-3β axis and VEGF-A expression." (PMID 37525212, 2023). "Previous studies have shown that LUCAT1 promoted proliferation and invasion in clear cell renal cell carcinoma cells through the AKT/GSK-3β signalling pathway." (PMID 32922538, 2020). "Significant upregulation of LUCAT1 in clear cell renal cell carcinoma (ccRCC) samples has been reported, and in fact, LUCAT1 overexpression induces proliferation, migration and invasion of ccRCC cells by inducing AKT and suppressing GSK3β." (PMID 39594666, 2024).
fibrosis (10 papers, 2020 to 2025). the formation of excess fibrous connective tissue in an organ or tissue in a reparative or reactive process. "In summary, Renalase regulates GSK-3β/Snail by regulating ER stress to inhibit TGF-β1-induced renal tubular epithelial cell fibrosis in vitro." (PMID 37082730, 2023). "In AF, activation of β-catenin may result from enhanced Akt/GSK-3β/β-catenin signaling, which induces atrial fibrosis." (PMID 40066352, 2025). "Moreover, we discuss the relationship between GSK-3β and ROS in fibrosis and the relationship between GSK-3β and aging-related fibrosis." (PMID 33052244, 2020). "Therefore, GSK-3β can be used as a new target to delay aging and aging-related fibrosis." (PMID 33052244, 2020).
Hypertension (10 papers, 2014 to 2025). The presence of chronic increased pressure in the systemic arterial system. "The aim of this study was to immunohistochemically evaluate and compare the expression of the Fzd8, WNT1, GSK-3β, and β-catenin genes in the hearts of rats with spontaneous hypertension (SHRs) and deoxycorticosterone acetate (DOCA)-salt-induced hypertension." (PMID 38928134, 2024). "In mice with hypertension under training (swimming, 150 min, 5 days/13 weeks) conditions, PKB phosphorylation is significantly improved and is associated with increased GSK-3β phosphorylation." (PMID 36036015, 2022). "In the left ventricle of mice with hypertension under exercise (70% of VO2max), PKB phosphorylation is significantly increased compared with mice with sedentary hypertension and PKB phosphorylation has significantly correlated with GSK-3β phosphorylation." (PMID 36036015, 2022). "GSK‐3β contributes to inflammatory cardiovascular and renal diseases, but its role in Aldo‐induced hypertension, and renal damage is not clear." (PMID 29600538, 2018).
osteoarthritis (10 papers, 2017 to 2025). A noninflammatory degenerative joint disease occurring chiefly in older persons, characterized by degeneration of the articular cartilage, hypertrophy of bone at the margins and changes in the synovial membrane. "Meanwhile, GSK‐3β inhibition also suppresses β‐catenin pathway activity, attenuates the apoptosis, and facilitates knee function in osteoarthritis model." (PMID 38334255, 2024). "In osteoarthritis, the decrease of GSK3B activity leads to the accumulation of β-catenin protein in the cytoplasm." (PMID 35747513, 2022). "A study showed that Smurf2 interacts with GSK-3β and induces its ubiquitination and subsequent proteasome degradation, activating the β-catenin signaling pathway, thereby aggravating osteoarthritis in mice." (PMID 35747513, 2022). "Short term β-catenin upregulation in cartilage secondary to Gsk3-β inhibition may be sufficient to induce osteoarthritis-like features in vivo." (PMID 31829205, 2019). "The GSK3β/β-CATENIN pathway is activated in the mandibular condylar cartilage, leading to a significant increase in the expression of osteoarthritis-related cytokines." (PMID 39010104, 2024). "In addition, inhibition of the Wnt/GSK-3β/NF-κB signaling axis can directly suppress MMP3 promoter activity, thereby ameliorating the progression of osteoarthritis." (PMID 40918434, 2025).
psychosis (10 papers, 2008 to 2025). "Abnormal activation of GSK-3β signaling pathways is implicated in the etiology of psychiatric disease; inhibition of the kinase has been proposed to be of therapeutic benefit in psychosis and bipolar diseases." (PMID 25120104, 2015). "The Wnt-related protein that has been consistently associated with BP or MDD is GSK3β; however, this molecule is at the crossroads between other signalling pathways that also appear to be involved in mood and psychotic disorders." (PMID 23449817, 2012). "Involvement of GSK-3β in psychotic disorders is already evidenced and mood stabilizers have been shown to modulate GSK-3β activity." (PMID 27579985, 2016). "The Akt/GSK3β/mTORC1 pathway has long been recognized as a point of convergence and etiological mechanism, but despite evidence suggesting its hypofunction, it is still not clear if this is already established during the first episode of psychosis (FEP)." (PMID 35757972, 2022). "Whether Akt/GSK3β/mTOR pathway hypofunction is an early event already established during the first episode of psychosis (FEP) can only be approached by assaying peripheral tissue." (PMID 35757972, 2022). "Our results show that lower expression of DVL2 and to a lesser extent higher expression of GSK3B are associated with more severe negative but not positive symptoms in psychosis." (PMID 24236287, 2013). "Intriguingly, psychotomimetics of two different classes, phencyclidine and D-lysergic acid, also had the same effects on GSK-3β, which may imply that substance-induced psychosis might be the result of a reduction in GSK-3 signaling." (PMID 18702828, 2008). "This pattern indicates an interesting overlap between ketamine, clozapine, and lithium with respect to the effects on GSK3β, suggesting that clozapine and lamotrigine’s effects on countering ketamine-related mania/psychosis may be mediated by the effects on glutamatergic transmission." (PMID 41304907, 2025).
type 1 diabetes (10 papers, 2005 to 2024). "The results from this study demonstrate that AKAP150 is a main ingredient of BK channel suppression through the Akt/GSK3β signalling pathway that thus contributes to vascular dysfunction during type 1 diabetes." (PMID 32163656, 2020). "Taken together with our prior observations, these data establish a role of increased GSK3β activity in the pathogenesis of parasympathetic dysfunction in type 1 diabetes via the regulation of IKACh and GIRK1/4 expression." (PMID 30978208, 2019). "Activation of GSK3β also ameliorates renal injury in STZ-induced type 1 diabetes." (PMID 33562139, 2021). "HNCP can also improve glucose metabolism in STZ-induced type 1 diabetic mice by regulating the expression levels of glycosynthesis- and gluconeogenesis-related enzymes such as GK, PEPCK1, G6Pase, and GSK-3β." (PMID 37888453, 2023). "Taken together, the current experimental data showed that type 1 diabetes impaired myocardial AMPK signaling and AKT/GSK-3β/HIF-1α signaling." (PMID 29088824, 2017). "Hence, our results suggest that during type 1 diabetes, AKAP150 is an important component of BK channel suppression through the Akt/GSK3β signalling pathway that contributes to vascular dysfunction." (PMID 32163656, 2020).
acute liver failure (9 papers, 2012 to 2023). Rapid deterioration of liver function causing encephalopathy and coagulopathy. "Although, GSK3β inhibition effectively protected mice and rats from endotoxin shock, its role in acute liver failure induced by D-GalN/LPS needs to be explored, and the underlying mechanisms of its hepatoprotective effects in vivo is also needed to be elucidated." (PMID 23028846, 2012). "Still, further studies are needed to explore the therapeutic effects of applying specific GSK3β inhibitors after acute liver failure, and the potential therapeutic window for the administration of inhibitors after injury." (PMID 37443080, 2023). "Inhibition of GSK3β has been reported as an effective hepatoprotective approach for liver injury induced by ischemia-reperfusion as well as for acute liver failure (ALF) induced by D-galactosamine and lipopolysaccharide (D-GalN/LPS)." (PMID 32961796, 2020). "In rodent models of acute liver failure, acetaminophen-induced hepatotoxicity and liver I/R injury, GSK-3β activation has been demonstrated." (PMID 31771282, 2019). "Our previous studies have demonstrated that inhibition of glycogen synthase kinase 3β (GSK3β) activity protects mice from acute liver failure (ALF), whereas its protective and regulatory mechanism remains elusive." (PMID 27010852, 2016). "Our previous studies have demonstrated that glycogen synthase kinase 3β (GSK3β) activity is increased in the progression of acute liver failure (ALF), which aggravates liver injury, while its regulatory mechanism remains elusive." (PMID 24531650, 2014). "We aimed to determine therapeutic potential of GSK3β inhibition and its mechanism in a well-characterized model of lipopolysaccharide (LPS)-induced model of acute liver failure (ALF)." (PMID 23028846, 2012). "GSK3β has been shown to regulate macrophage cytokine production and hepatocyte apoptosis, however, its role in acute liver failure–the inflammation and apoptosis-mediated hepatocellular injury process–has not been explored." (PMID 23028846, 2012). "The current study reveals critical roles of GSK3β in acute liver failure through defined down-stream pathways." (PMID 23028846, 2012). "However, it is of concern that our current work is focused on the preventive effect of GSK3β inhibition on acute liver failure, although some studies have shown that TDZD-8 has some preventive and therapeutic value in ischemia–reperfusion injury." (PMID 37443080, 2023). "In addition to their proposed antiviral effects, GSK3β inhibitors were shown to be protective against acute liver failure." (PMID 28566716, 2017). "Thus, inhibition of GSK3β activity could improve cell death levels in acute liver failure by modulating the activity levels of the TRAF6/HDAC3/TAK1 molecular pathway." (PMID 37443080, 2023). "In an acute liver failure (ALF) mice model, GSK3β inhibition promotes autophagy to inhibit liver inflammation, indicating that GSK3β is involved in the hepatoprotective mechanisms though autophagic pathways." (PMID 31683987, 2019).
asthma (9 papers, 2014 to 2025). "GSK3β is known to regulate the activity of NF-κB, which has been associated with the development of asthma." (PMID 24667347, 2014). "Glycogen synthase kinase 3β (GSK3B), whose elevation has been shown to be associated with asthma." (PMID 40160461, 2025). "Notably, three common target genes—cyclin D1 (CCND1), vascular endothelial growth factor A (VEGFA), and glycogen synthase kinase-3 beta (GSK3B)—were identified as being regulated by all three miRNAs within pathways associated with asthma and inflammation." (PMID 38279356, 2024). "Another protein kinase glycogen synthase kinase-3β (GSK-3β) is also linked to asthma pathology." (PMID 36078171, 2022). "Salidroside has also been reported to alleviate inflammatory cell infiltration in OVA-induced asthma mouse models, suppress IL-4, IL-5, and IL-13 expression, and reduce phosphorylation of Akt and GSK3β." (PMID 40490797, 2025). "Our analyses also found that GSK3B was upregulated in bronchoalveolar lavage fluid in asthma and positively correlated with asthma severity." (PMID 40160461, 2025). "MiR-140 suppresses airway inflammation and inhibits bronchial epithelial cell apoptosis in asthma by targeting GSK3β." (PMID 38173723, 2023). "Airway smooth muscle hyperplasia and hypertrophy correlate with GSK-3β phosphorylation in a mouse model of asthma." (PMID 36078171, 2022). "Vice versa, asthma could be improved under conditions, in which an activation of GSK3β could be observed, such as the application of dexamethasone or Louki Zupa decoction." (PMID 39125833, 2024). "Recently, it has been shown that inhibition of GSK-3β resulted in increased suppression activity by Treg cells, suggesting GSK3β-mediated Treg insufficiency may be considered a therapeutic target for the management of asthma." (PMID 24667347, 2014). "GSK3β is a serine-threonine kinase that is constitutively active in cells and has recently been demonstrated to play a critical role in the pathophysiology of asthma by regulating NF-κB activation." (PMID 24667347, 2014). "The cytokine IL-6 was recently shown to induce migration of bronchial epithelial cells in PI3K/Akt/GSK-3β/β-catenin dependent manner suggesting that this pathway may be contributing to the mesenchymal population of cells often found in asthma through induction of EMT signals." (PMID 25413472, 2014). "PTGS2, IL10, CTSB, JAK2, and MTOR were significantly downregulated in alveolar lavage fluid with increasing asthma severity, while MMP9, GSK3B, BCL2, EGFR, and CCND1 were upregulated." (PMID 40160461, 2025). "The top 10 highest degree of targets were EGFR, JAK1/2, MAPK14, VEGF, SRC, mTOR, PI3K, and GSK3B, which might be the critical targets of HHAE for the treatment of asthma." (PMID 36408342, 2022).
endotoxemia (9 papers, 2009 to 2021). "For example, inhibition or deletion of GSK3β was protective against experimental peritonitis and arthritis, renal dysfunction and hepatotoxicity associated with endotoxemia, and endotoxin shock." (PMID 25541965, 2014). "To clarify the protective effect of isoorientin on the brain, we detected the inflammatory cytokines in peripheral and central nervous systems, the BBB integrity, and the p-GSK3β (Ser9) in the brain of endotoxemia mice." (PMID 33192176, 2020). "Isoorientin (25 and 50 mg/kg) and LiCl (100 mg/kg) upregulated the expression of occludin, ZO-1 and p-GSK3β in the brain of endotoxemia mice, showing a good potential of reversing the destruction of BBB and treatment for GSK3β-related brain diseases." (PMID 33192176, 2020). "This study investigated the effects of isoorientin on the inactive form GSK3β (phosphorylation at Ser9) and its downstream signal molecules in macrophages, as well as the protective effect on the brain in endotoxemia mice." (PMID 33192176, 2020). "Isoorientin inhibited inflammatory responses in endotoxemia mice, increased p-GSK3β (Ser9), and protected the integrity of BBB by increasing the tight junction protein occludin and ZO-1 in the brain." (PMID 33192176, 2020). "GSK‐3β positively regulated the expression of FOXO3A via degrading β‐catenin in endotoxemia cardiac dysfunction." (PMID 31503410, 2019). "We evaluate visuospatial memory, cytokines levels, and the expression of tau and GSK-3β proteins in hippocampus and cortex of animals exposed to neonatal endotoxemia." (PMID 31467920, 2019). "This fits well with some studies in endotoxemia model where the protective effects of GSK-3β inhibitors on cytokine production and organ dysfunction were identified." (PMID 26218875, 2015). "Mice treated with GSK-3β inhibitors showed decreased renal cell apoptosis in response to endotoxemia." (PMID 25525303, 2014). "Recent studies have demonstrated that GSK-3β inhibition protects renal cell from endotoxemia and attenuates liver I/R injury via inhibition of apoptosis." (PMID 25525303, 2014). "Recently, more and more data suggest that GSK3β plays a detrimental role in the pathogenesis of AKI in animal models exposed to nephrotoxic substance or subjected to renal ischemia/reperfusion injury or endotoxemia." (PMID 34195206, 2021). "Thus, the objective of this study is to evaluate visuospatial memory, cytokines levels, and the expression of tau and GSK-3β proteins in hippocampus and cortex of animals exposed to neonatal endotoxemia." (PMID 31467920, 2019). "This study provided good evidence for clarifying the role of isoorientin in endotoxemia by protecting the BBB and regulating p-GSK3β in the brain." (PMID 33192176, 2020). "The present study investigated the anti-inflammatory effect and mechanism of isoorientin via GSK3β regulation in lipopolysaccharide- (LPS-) induced RAW264.7 murine macrophage-like cells and endotoxemia mice." (PMID 33192176, 2020). "For instance, GSK-3β inhibitors TDZD-8 and SB216763 reduced NF-κB mediated inflammation in rats with endotoxemia, and protected tissue damage in CIA mice." (PMID 19712471, 2009). "However, there were no statistically significant alterations in the evaluations of GSK-3β protein expression in hippocampus and TAU protein in hippocampus and cortex (p> 0.05) after 60 days of endotoxemia." (PMID 31467920, 2019).
hyperlipidemia (9 papers, 2011 to 2026). "Furthermore, local inhibition of GSK3β significantly attenuates alveolar bone destruction in a hyperlipidemia-associated periodontitis mouse model." (PMID 41945797, 2026). "Studies have shown that the PTEN inhibitor bisperoxovanadium can restore the cardioprotective effect of RIC in hyperlipidemia rats, which may be related to promoting downstream Akt/GSK-3β phosphorylation." (PMID 36072870, 2022). "In hyperlipidemia research, pharmacological inhibition of GSK-3β may be a promising future therapeutic target." (PMID 36072870, 2022). "Regarding body weight, a double knockdown of both Gsk3a and Gsk3b led to a decrease in body weight, whereas an overexpression of human GSK3B in mice skeletal muscle resulted in impaired glucose tolerance, hyperlipidemia and an increase in fat mass and body weight gain." (PMID 31801236, 2019).